TMEM63A (transmembrane protein 63A)
Description:
Mechanosensitive cation channel with low conductance and high activation threshold. In contrast to TMEM63B, does not show phospholipid scramblase activity. Acts as a regulator of lysosomal morphology by mediating lysosomal mechanosensitivity (By similarity). Important for the baby's first breath and respiration throughout life. Upon lung inflation conducts cation currents in alveolar type 1 and 2 cells triggering lamellar body exocytosis and surfactant secretion into airspace. Also acts as an osmosensitive cation channel preferentially activated by hypotonic stress (By similarity).
Synonyms: hTMEM63A; KIAA0792; HLD19
Tractability: Small molecule: a structure with a bound ligand is known. Antibody: UniProt places it where antibodies can reach, with high confidence; its Gene Ontology location is reachable by antibodies, with high confidence; UniProt predicts a signal peptide or a membrane-spanning region. PROTAC: ubiquitination databases record sites on it; its protein half-life has been measured.
Gene: Protein-coding gene on chromosome 1 (225,845,536 to 225,884,071, reverse strand). Ensembl gene ENSG00000196187.
Subcellular location: Lysosome membrane; Early endosome membrane; Cell membrane
Subcellular location (Human Protein Atlas): Centriolar satellite; Vesicles
Pathways (Reactome):
Immune System: Neutrophil degranulation
Gene Ontology:
Molecular function: mechanosensitive monoatomic ion channel activity; phospholipid scramblase activity; protein binding; osmolarity-sensing monoatomic cation channel activity; calcium-activated cation channel activity; nucleic acid binding
Biological process: lysosome organization; surfactant secretion; monoatomic cation transmembrane transport; monoatomic ion transmembrane transport
Cellular component: centriolar satellite; early endosome membrane; extracellular exosome; lysosomal membrane; plasma membrane; specific granule membrane; tertiary granule membrane; membrane
Genetic constraint (gnomAD): Loss-of-function variants: 71 observed, 103.09 expected, observed/expected ratio (o/e) 0.69, 90% interval 0.57 to 0.84. The upper end of that interval is the gene's LOEUF score, 0.84, which puts it in group 3 of 6, group 1 being the genes least tolerant of losing a copy. Missense variants: 873 observed, 1,030.7 expected, observed/expected ratio (o/e) 0.85, 90% interval 0.8 to 0.9. Synonymous variants: 400 observed, 410.26 expected, observed/expected ratio (o/e) 0.98, 90% interval 0.9 to 1.06.
Homologues: Orthologues: chimpanzee TMEM63A (99% identical), macaque TMEM63A (98% identical), pig TMEM63A (90% identical), mouse Tmem63a (90% identical), dog TMEM63A (89% identical), rat Tmem63a (88% identical), rabbit TMEM63A (87% identical), guinea pig TMEM63A (82% identical), tropical clawed frog tmem63a (65% identical), zebrafish tmem63a (53% identical). Paralogues in human: TMEM63B (55% identical), TMEM63C (39% identical).
Diseases named in the same sentence as TMEM63A in open-access papers:
TMEM63A is named in the same sentence as 11 diseases in open-access papers, as found by Europe PMC text mining. Sharing a sentence is not in itself a finding about the gene and the disease. The quoted sentences say what the papers report.
leukodystrophy (3 papers, 2022 to 2025). Leukodystrophies are a group of rare, progressive, metabolic, genetic diseases that affect the brain, spinal cord and often the peripheral nerves. "Tmem63a may modulate chronic post-amputation pain, and mutations in TMEM63A are associated with transient hypomyelination during infancy and hypomyelinating leukodystrophy." (PMID 41348674, 2025). "Recently, heterozygous missense mutations in the transmembrane protein 63A (TMEM63A) gene were identified in a hypomyelinating leukodystrophy that usually presents in the first weeks of life with nystagmus, neurological abnormalities, and hypomyelination by MRI." (PMID 36003149, 2022).
respiratory failure (2 papers, 2024). The significant impairment of gas exchange within the lungs resulting in hypoxia, hypercarbia, or both, to the extent that organ tissue perfusion is severely compromised. "Deficiency of TMEM63A/B resulted in surfactant insufficiency in alveoli, which subsequently caused atelectasis and respiratory failure." (PMID 38127458, 2024). "Here, we show that loss of the mechanosensitive channels TMEM63A and TMEM63B (TMEM63A/B) resulted in atelectasis and respiratory failure in mice due to a deficit of surfactant secretion." (PMID 38127458, 2024). "TMEM63A/B KO results in atelectasis, pulmonary edema, and respiratory failure." (PMID 38127458, 2024). "Thus, the mouse studies by Chen, Li, and colleagues show that inducible TMEM63A/B codeletion in AT2 cells caused pulmonary edema and death and that adding TMEM63A/B deletion in AT1 cells to the AT2 cell TMEM63A/B deletion model accelerated the respiratory failure." (PMID 38426500, 2024).
deafness (1 paper, 2024). An inherited or acquired condition characterized by the complete loss of the ability to hear from one or both ears. "The deafness-associated mutation is located in TM 4 (equivalent of M522 in TMEM16F, I547 in TMEM16A, A439 in OSCA1.2, and A476 in TMEM63A) and results in constitutive PS exposure when expressed in the hair cell membranes of both heterozygous and homozygous mice." (PMID 39495104, 2024).
neuroma (1 paper, 2023). A tumor that grows from a nerve or is composed of nerve cells and nerve fibers. "This showed that the expression level of Tmem63a in neuromas was about double that in nerve tissues, suggesting a potential role of TMEM63A in the CPAPs." (PMID 35821338, 2023). "Using Tmem63a-/- mice with exons 3–5 deleted and human neuroma samples, we made several interesting findings." (PMID 35821338, 2023). "First, Tmem63a was specifically expressed in DRG neurons, especially in the non-peptidergic nociceptors, and its expression was significantly increased in human neuroma and the DRGs of mice subjected to TNT surgery." (PMID 35821338, 2023). "Then we assessed the expression of Tmem63a in the DRGs of the mouse TNT model, and found it was significantly elevated, but not in the PTX-induced chemotherapy model, which was consistent with the data from the human neuroma sample." (PMID 35821338, 2023).
triple-negative breast carcinoma (1 paper, 2022). An invasive breast carcinoma which is negative for expression of estrogen receptor (ER), progesterone receptor (PR), and human epidermal growth factor receptor 2 (HER2). "In triple-negative breast cancer, TOLLIP-mediated autophagy can hinder disease progression via the degradation of transmembrane protein 63A (TMEM63A), a novel oncogene that promotes cancer cell proliferation in triple-negative breast cancer." (PMID 36499030, 2022).
neurodevelopmental disorder (1 paper, 2024). A behavioral and cognitive disorder with onset during the developmental period that involves impaired or aberrant development of intellectual, motor, or social functions. "As genetic variants of TMEM63A/B/C have been identified in patients with neurodevelopmental disorders, further studies are required to understand the functions of TMEM63 channels in the nervous system." (PMID 38127458, 2024).
TMEM63A also shares sentences with these, for which no sentence is quoted: cancer (1 paper); edema (1); Nystagmus (1); Tremor (1); tumor (1).